HAS2 (hyaluronan synthase 2)
Diseases named in the same sentence as HAS2 in open-access papers (continued):
Sharing a sentence is not in itself a finding about the gene and the disease.
lymphoma (1 paper, 2013). A malignant (clonal) proliferation of B- lymphocytes or T- lymphocytes which involves the lymph nodes, bone marrow and/or extranodal sites. "Furthermore, chemoresistant lymphoma cell lines were also found to have greater expression of Has1, Has2, and Has3 transcripts, and to secrete higher levels of HA." (PMID 24124770, 2013).
memory impairment (1 paper, 2025). "Treatment with 4‐MU reduced infarct volume and improved learning and memory impairments by downregulating HAS1 and HAS2." (PMID 41355840, 2025).
metastatic cancers (1 paper, 2021). A carcinoma which has spread from the original site of growth to another anatomic site. "MAF-specific knockout of HGF and HAS2 decreases metastatic tumor growth and strongly extends the survival of mice, suggesting that HGF and HAS2 may be therapeutic targets for desmoplastic metastatic cancers." (PMID 34112258, 2021).
metastatic tumor (1 paper, 2025). "Because our study revealed the procarcinogenic and prometastatic role of HAS2 and HA, modulation of HAS2 and HA production can be a therapeutic strategy to inhibit metastatic tumor growth in steatotic liver." (PMID 39946200, 2025).
middle ear inflammation (1 paper, 2025). "As regards middle ear inflammation, increased Has2 expression and subsequent HA accumulation may contribute to mucosal thickening, exudate formation, and persistent IR characteristic of CSOM13." (PMID 41258032, 2025). "However, the specific roles of Has2 and HA metabolisms in chronic middle ear inflammation warrant further investigation to obtain sufficient understanding of their mechanistic contributions to CSOM pathogenesis." (PMID 41258032, 2025).
Miscarriage (1 paper, 2013). A pregnancy that ends at a stage in which the fetus is incapable of surviving on its own, defined as the spontaneous loss of a fetus before the 22th week of pregnancy. "Furthermore, the HAS2 mRNA level in DSCs from the normal pregnancy was much higher than that of miscarriage." (PMID 24069351, 2013).
mucinosis (1 paper, 2022). "In fact, there was a higher transcription of hyaluronan synthase 2 and protein expression in fibroblasts, indicating a relationship between cutaneous mucinosis and the genetic cause related to this enzyme." (PMID 36006348, 2022). "HAS proteins facilitated the extrusion of hyaluronan to the extracellular space, and this could explain the relationship between mucinosis in the Shar-Peis and high levels of HAS2 protein expression and hyaluronan accumulation." (PMID 36006348, 2022).
multiple myeloma (1 paper, 2015). "Altered HAS enzymes function has been implicated in multiple myeloma (HAS1), in renal-controlled fluid balance, heart formation, long bone/spine development, wound healing (HAS2), and seizures (HAS3)." (PMID 26448758, 2015).
myocardial infarction (1 paper, 2025). Gross necrosis of the myocardium, as a result of interruption of the blood supply to the area, as in coronary thrombosis. "We recently showed that activated fibroblasts produce hyaluronan via Has2; however, the extent to which this function impacts acute ventricular remodeling following myocardial infarction (MI) has not been tested." (PMID 41250926, 2025).
prostate adenocarcinoma (1 paper, 2023). "Similarly, HAS2 exhibited significant downregulation in BLCA, BRCA, KICH, KIRC, kidney renal papillary cell carcinoma (KIRP), LIHC, LUAD, LUSC, prostate adenocarcinoma (PRAD), and UCEC tumors." (PMID 37636435, 2023).
rheumatoid arthritis (1 paper, 2015). A chronic, systemic autoimmune disorder characterized by inflammation in the synovial membranes and articular surfaces. "Interestingly, the expression of both HAS1 and HAS2 was reduced in the synovium of patients with osteoarthritis or rheumatoid arthritis compared to healthy controls." (PMID 25699059, 2015).
scoliosis (1 paper, 2022). A congenital or acquired spinal deformity characterized by lateral curvature of the spine. "Since this site is near the HAS2 gene (hyaluronan synthase 2), playing a critical role in vertebral and intervertebral disc development, they speculated cg01374129 hypomethylation deregulates HAS2 expression, impairing normal spine development and causing scoliosis progression." (PMID 35682604, 2022).
skin aging (1 paper, 2023). The gradual irreversible changes in structure of skin that occur as a result of the passage of time.. "Pure inotodiol/inotodiol concentrate could also modulate the synthesis of collagen and hyaluronic acid by controlling COL1A2 and HAS2/3 expression, which implies a crucial role for inotodiol/inotodiol concentrate in the prevention of skin aging." (PMID 37628993, 2023). "Moreover, pure inotodiol/inotodiol concentrate could also modulate the synthesis of collagen and hyaluronic acid by controlling COL1A2 and HAS2/3 expression, which implies a crucial role for pure inotodiol/inotodiol concentrate in the prevention of skin aging." (PMID 37628993, 2023).
Stroke (1 paper, 2025). Sudden impairment of blood flow to a part of the brain due to occlusion or rupture of an artery to the brain. "Similarly, Hyal1, Hyal2, and Has2 mRNAs become upregulated in peri-infarct tissues in a rat model of stroke induced by occlusion of the middle cerebral artery." (PMID 41586378, 2025). "As in previous studies, they observed upregulation of mRNAs of genes encoding HA synthesizing and degrading enzymes in the perilesional area at early times after stroke, and immunostaining showing increased Hyal1 in astrocytes and Has2 in astrocytes and neurons." (PMID 41586378, 2025). "Elevated HAS1, HAS2, HYAL1, and HYAL2 were also found in post-mortem brain tissue of stroke patients, and elevated HYAL1 was observed in serum from stroke patients." (PMID 41586378, 2025).
teratocarcinoma (1 paper, 2022). A germ cell tumor characterized by the presence of an embryonal carcinoma component and a teratoma component. "HAS1, HAS2 and HYAL3 expression levels showed to be comparable in all adenocarcinoma cell lines SKOV-3, Caov-3 and SW 626 cells, whereas the teratocarcinoma cell line PA-1 cells expressed higher levels of all the three genes." (PMID 35767191, 2022).
Thrombocytopenia (1 paper, 2025). A reduction in the number of circulating thrombocytes. "Megakaryocytes (MKs), the platelet progenitor cell, express only HAS2 and HAS3, and dysregulated metabolism of HA by MKs leads to thrombocytopenia." (PMID 41586377, 2025).
tumor (119 papers, 2009 to 2025). "In PC, the accumulation of HA in the tumor microenvironment, mediated by the HAS2 gene, is associated with higher migration, tumor growth, angiogenesis, and a worse prognosis." (PMID 41296417, 2025). "HAS2 has been implicated in promoting tumor aggressiveness and the formation of the extracellular matrix, which contributes to GBM growth and invasion." (PMID 37636435, 2023). "Tumor-associated mesenchymal stem cells increase HA levels in the ECM by upregulating HA synthase-2 (HAS2) expression." (PMID 35204054, 2022). "When Has2-deficient Has2Δ/Δ cancer cells were then transplanted into the mammary fat pads of nude mice, tumor growth was significantly suppressed as compared with that of the control Has2flox/flox group." (PMID 31645543, 2019). "HAS2 has also been implicated as a regulator of cell senescence and proliferation, with suppression of HAS2 in tumor cells arresting the cell cycle in the G1 phase." (PMID 31352003, 2019). "Pancreatic tissue-resident, tumor-associated macrophages express hyaluronan synthase 2 and 3 and display a pro-fibrotic phenotype in transgenic mouse models of PDAC." (PMID 31490946, 2019). "For example, HAS2 is a member of the gene family encoding putative hyaluronan synthases, which control the biosynthesis of hyaluronan and critically modulate the tumor microenvironment." (PMID 30540749, 2018). "Here, we show that tumor-associated mesenchymal stem-like cells (tMSLCs) contribute to abundance of hyaluronic acid (HA) in tumor microenvironment through HA synthase-2 (HAS2) induction, and thereby enhances invasiveness of GBM cells." (PMID 27903965, 2017). "Using genetic manipulation and chemical inhibition of HA synthesis we have demonstrated that HAS2 dependent HA synthesis is a major driven of tumor growth with AGL loss." (PMID 27595989, 2016). "The overexpression of HAS2 has been observed in some solid cancers in which it is associated with more aggressive tumor phenotypes." (PMID 27884164, 2016). "Hyaluronan synthetase, HAS2 overexpression and amplification have been implicated in tumor proliferation and metastasis in genitourinary tumors." (PMID 25369402, 2014). "Currently mass spectrometric analysis is underway to decipher AGL-effector protein interactions to understand how loss of AGL might result in elevated HAS2 expression and aggressive tumor growth." (PMID 29682180, 2018). "Together, these results suggested that CAFs expressed higher levels of HAS2 and that HAS2 from the tumor stromal microenvironment may be associated with tumorigenesis." (PMID 27884164, 2016). "HAS2 is responsible for the synthesis of hyaluronan (HA), a glycosaminoglycan with a demonstrated role in cancer initiation and progression and whose elevated accumulation in either the stroma or tumour parenchyma of many cancers is linked to tumour aggressiveness and poor outcome." (PMID 33692466, 2021). "Furthermore, our data revealed the role of TGIF1 in regulating TGFβ-induced hyaluronan synthase 2 (HAS2) activity, which has a profound effect on tumor-associated macrophage (TAM) polarization; moreover, TGIF1 exhibits an antitumor immunity potential through the suppression of PD-L1 expression." (PMID 31109321, 2019). "Conditional knockout of Has2 in CAFs resulted in reduced hyaluronan production and, consequently, smaller tumour sizes in preclinical models." (PMID 39780187, 2025). "HAS2 expression is also regulated by interleukin-1β, FGF-2, PDGF, KGF, EGF, and TGF-β in tumor-associated fibroblasts." (PMID 39851489, 2025). "It is likely that HAS1 and HAS3 act cooperatively with HAS2 to support HA deposition and tumor growth." (PMID 39946200, 2025). "HAS1 expression was significantly higher in the tumor stage compared to the patch stage, whereas expression of HAS2 and HAS3 was moderate to strong in all disease stages." (PMID 39858106, 2025).
tumor (continued). "In this case, a certain protein synthesized by the cells of the tumor itself, C10 or f118, is indicated as a stimulus for HAS2 hyperexpression." (PMID 39851489, 2025). "In patients with PDAC, the inhibition of IRAK4 phosphorylation in tumor cells downregulates Hyaluronan synthase 2 (HAS2) through an NF-κB-dependent mechanism." (PMID 39744438, 2025). "It is believed that the overexpression of the enzymes SHMT2 and HAS2 with AGL loss drives increased synthesis of glycine and hyaluronic acid, leading to enhanced glucose absorption and metabolism that promotes rapid tumor proliferation and growth." (PMID 39858027, 2025). "We found that a fibrotic TME and HAS2 contribute to YAP activation in cancer cells and the development of a prometastatic immunosuppressive TME comprising M2 tumor-associated macrophages (TAMs) and exhausted CD8+ T cells." (PMID 39946200, 2025). "We investigated the role of HA synthase 2 (HAS2) in the fibrotic tumor microenvironment in steatotic liver using Has2ΔHSC mice, in which Has2 is deleted from hepatic stellate cells." (PMID 39946200, 2025). "Hyaluronan synthase-2 (HAS2) depletion in fibroblasts resulted in reduced macrophage recruitment, increased angiogenesis, and lymphangiogenesis at the tumor site." (PMID 38035101, 2023). "Among these proteins, expression levels of Col4A5, GPC1 and HAS2 increased progressively with metastatic potential or tumor size in cell and animal experiments, respectively." (PMID 37903851, 2023). "Depletion of hyaluronan synthase 2 in cancer-associated fibroblasts reduces TAM recruitment and thereby attenuates tumor angiogenesis and lymphangiogenesis." (PMID 35366828, 2022). "According to the levels of HA synthesis, the expression of the HAS2 led to aggressive cancer progression, but at high levels, the tumor growth was markedly reduced." (PMID 36613567, 2022). "The results show that HAS1 was overexpressed in effusions, HAS2 was overexpressed in solid metastases and primary tumours, and HAS3 was overexpressed in primary carcinomas and effusions." (PMID 35767191, 2022). "The fact that low expression of HAS2 is correlated with lower tumour cell growth is strengthened by the results of String analysis that HAS1-3 interact close with UGDH." (PMID 35767191, 2022). "The results showed that both KLF7 and HAS2 were downregualted in shKLF7 tumor tissues as compared shCtrl tissues." (PMID 33892667, 2021). "Concomitantly, the use of a specific HAS2 inhibitor would induce a reduction of the stroma content by decreasing HA synthesis by CAFs further contibuting to tumour growth/aggressiveness wane." (PMID 33692466, 2021). "This is further supported by gene expression analysis, where CAFs isolated from Osm−/− tumours exhibited decreased inflammatory gene expression (e.g. Il6, Mmp3, Has2 and Osmr) but increased myofibroblast gene expression (e.g. Acta2, Itgav and Fn1)." (PMID 34921158, 2021). "Once it is removed by either knocking down HAS2 or overexpressing the HA-degrading enzyme, HYAL2, naked mole-rat cells become susceptible to malignant transformation and easily form tumours." (PMID 34944493, 2021). "Taken together, we reveal that GNA14/KLF7/HAS2 signaling cascade exerts tumor promoting function during UCEC development." (PMID 33892667, 2021). "Tumor site-specific delivery of modulators of circ_102002/miR-488-3p/HAS2 axis or combination with other approaches will offer new opportunities to design innovative therapeutic strategies for PTC." (PMID 32862195, 2021). "SPHK1 and HAS2 have previously been demonstrated to be upregulated in several types of human cancer and to play an important role in tumor development and progression, including cellular motility and cellular proliferation and angiogenesis." (PMID 33506044, 2021). "Differential gene expression testing comparing HAS2-high vs. HAS2-low tumor samples was performed, and we identified 123 genes with significantly altered levels." (PMID 32455980, 2020).
tumor (continued). "Collectively, these data support the concept that VDR suppresses HAS2 and HA production in both normal mammary gland and in tumor cells in vivo." (PMID 32774770, 2020). "As NF-κB signaling is known to regulate the expression of HAS2, we detected activated p65 in the tumor tissue from xenografts by immunofluorescence." (PMID 30705401, 2019). "An example of evidence supporting this latter function is provided by the enhanced invasion of tumor cells when they are transfected with both HAS2 and hyaluronidases." (PMID 31134064, 2019). "HAS2-mediated acceleration of tumor progression results in part from resistance to apoptosis caused by constitutive activation of PI3K/AKT signaling." (PMID 31134064, 2019). "Simpson and co-workers have shown that co-expression of HYAL1 and HAS2 is the most favorable combination for tumor formation in vivo, and in vitro overexpression of HAS2 decreases the growth of tumor cells compared to controls." (PMID 29914429, 2018). "We also show that HAS1, HAS2 and HYAL2 are associated with WHO grade, suggesting that they have a role in tumor progression." (PMID 29914429, 2018). "Irinotecan is topoisomerase inhibitor that in inhibits cell division and has been shown to repress tumor growth in cell lines with HAS2 over production." (PMID 27716027, 2016). "For example, up-regulation of HAS2 in breast cancer promotes the invasive potential of tumor cells by suppressing TIMP1." (PMID 27884164, 2016). "We then analyzed the relationship between HAS2 expression in the tumor stroma and clinical/pathological characteristics of the OSCC." (PMID 27884164, 2016). "Concurrently with diminished macrophage recruitment, ­Has2-null TAFs attenuated tumor angiogenesis and lymphangiogenesis." (PMID 26322272, 2015). "Recent studies on Has2 null fibroblasts showed severe impairment in recruiting macrophages when inoculated with tumour cells into nude mice, which demonstrates the contribution of stroma-derived hyaluronan in intratumoral macrophage mobilization." (PMID 25126569, 2014). "HA expression was identified diffusely in both tumor and stromal cells, whereas HAS2 and HYAL1 expressions were observed predominantly in tumor cells." (PMID 24244714, 2013). "Univariate analysis revealed significant prognostic factors, including UICC tumor stage, residual tumor, strong HA expression, strong HAS2 expression, and weak HYAL1 expression." (PMID 24244714, 2013). "Expressions of HAS1, HAS2 (HA synthases) and HYAL1 (hyaluronidase), have been shown to be associated with diagnosis and prognosis of various tumor types." (PMID 24244714, 2013). "All tumor samples also showed HAS2 signal in the cancer epithelial cells, but the staining intensity was more variable." (PMID 19435493, 2009). "Immunohistochemical stainings of HAS proteins showed a low level of HAS1, a slightly elevated level of HAS3 in the tumor epithelia, and a variable elevation of HAS2 immunostaining in the tumor epithelial cells, in agreement with the mRNA assays." (PMID 19435493, 2009). "We found that the levels of combination signatures CM-2 (HYAL-1 + N-Cadh) and CM-6 (HYAL-1 + N-Cadh + HAS-2 + SNAI1 + Slug + MMP-9) were elevated 5–8-fold in tumor specimens from patients who had or developed metastasis during follow-up compared to those who did not (p < 0.0001)." (PMID 40149256, 2025). "In addition, as a hyaluronan synthase (HAS2/3) inhibitor, 4-MU interfered with the HA-dependent tumor microenvironment and fibrosis process by inhibiting HAS2/3." (PMID 40839202, 2025). "Deletion of the other most upregulated gene in myCAF, hyaluronan synthase 2 (Has2), significantly reduces ICC tumor growth with an unknown mechanism due to the multiple hyaluronan receptors and multiple cell types of Has2-expressing myCAF." (PMID 40248197, 2025). "The dual targeting of FAS and HAS2/3 by 4-MU elicits synergistic anti-tumor effects in HCC." (PMID 40839202, 2025).